ZNF730 (zinc finger protein 730)
Description:
May be involved in transcriptional regulation.
Tractability: PROTAC: ubiquitination databases record sites on it.
Gene: Protein-coding gene on chromosome 19 (23,075,210 to 23,147,221, forward strand). Ensembl gene ENSG00000183850.
Subcellular location: Nucleus
Pathways (Reactome):
Gene expression (Transcription): Generic Transcription Pathway
Gene Ontology:
Molecular function: DNA-binding transcription factor activity, RNA polymerase II-specific; RNA polymerase II cis-regulatory region sequence-specific DNA binding
Biological process: regulation of DNA-templated transcription; regulation of transcription by RNA polymerase II
Cellular component: nucleus
Genetic constraint (gnomAD): Loss-of-function variants: 9 observed, 9.36 expected, observed/expected ratio (o/e) 0.96, 90% interval 0.58 to 1.64. That is too few expected variants to judge how well the gene tolerates losing a copy. Missense variants: 633 observed, 555.26 expected, observed/expected ratio (o/e) 1.14, 90% interval 1.07 to 1.22. Synonymous variants: 192 observed, 187.88 expected, observed/expected ratio (o/e) 1.02, 90% interval 0.91 to 1.15.
Homologues: Orthologues: chimpanzee ZNF92 (73% identical). Paralogues in human: ZNF98 (77% identical), ZNF92 (73% identical), ZNF737 (72% identical), ZNF66 (71% identical), ZNF675 (71% identical), ZNF723 (70% identical), ZNF257 (70% identical), ZNF431 (70% identical), ZNF430 (69% identical), ZNF680 (69% identical), ZNF273 (69% identical), ZNF626 (68% identical), and 6 more.
Diseases named in the same sentence as ZNF730 in open-access papers:
ZNF730 is named in the same sentence as 3 diseases in open-access papers, as found by Europe PMC text mining. Sharing a sentence is not in itself a finding about the gene and the disease. The quoted sentences say what the papers report.
cancer (1 paper, 2022). A tumor composed of atypical neoplastic, often pleomorphic cells that invade other tissues. "Genes containing AS events associated with overall survival are known components of cancer-related pathways, including regulation of transcription (E2F4, ZNF730, GPBP1, POLR2J, SP2, and CIART), cell cycle (E2F4 and GTSE1), or cell-cell adhesion (CEACAM1, MMP14, EPS8L2, AP3D1, AFDN, and PAK4)." (PMID 35044822, 2022).
ZNF730 also shares sentences with these, for which no sentence is quoted: gout (1 paper); tumour (1).